KDM6B (lysine demethylase 6B)
Diseases named in the same sentence as KDM6B in open-access papers (continued):
Sharing a sentence is not in itself a finding about the gene and the disease.
Intellectual disability (4 papers, 2019 to 2024). "KDM6B mutations are linked to a neurodevelopmental disorder that includes developmental delay, autistic features and intellectual disability, consistent with a possible mechanistic relationship between CHD8 and KDM6B." (PMID 38288845, 2024). "Similarly, the novel object recognition test showed that the mutant mice had impaired long-term object recognition memory, which is consistent with the clinical reports that most patients with KDM6B mutations have various degrees of intellectual disability with cognitive impairments." (PMID 35711692, 2022). "Furthermore, the KDM6B gene carries three additional de novo loss-of-function mutations in ASD patients, and three de novo missense mutations (one in ASD patient and two in the patients with intellectual disability), with no mutations observed in controls." (PMID 31199787, 2019).
liver fibrosis (4 papers, 2021 to 2023). "However, they contrast the previously outlined role of KDM6B in that they find that KDM6B has a protective role in kidney and liver fibrosis." (PMID 37476157, 2023). "Similarly, overexpression of KDM6B leads to an increase in Smad7 expression in liver fibrosis." (PMID 37476157, 2023).
pulmonary fibrosis (4 papers, 2018 to 2023). Chronic progressive interstitial lung disorder characterized by the replacement of the lung tissue by connective tissue, leading to progressive dyspnea, respiratory failure, or right heart failure. "Our animal experiments revealed that KDM6B expression levels were significantly upregulated in murine pulmonary fibrosis lungs and positively correlated with α-SMA and fibronectin expression, emphasizing its essential role in IPF pathogenesis and progression." (PMID 37275887, 2023). "The results demonstrated a significant positive correlation between KDM6B and key pulmonary fibrosis proteins, such as fibronectin and α-SMA." (PMID 37275887, 2023). "This study demonstrated increased KDM6B expression in the lungs of patients with IPF and in the bleomycin-induced pulmonary fibrosis mouse model, compared to healthy human lung tissue and control mice, respectively." (PMID 37275887, 2023). "KDM6B expression, along with macrophages, CD3+ and CD4+ T cells, was significantly elevated in the lungs of bleomycin-induced pulmonary fibrosis mice compared to healthy controls." (PMID 37275887, 2023). "Additionally, the pulmonary fibrosis-related proteins fibronectin and α-SMA exhibited strong correlations with KDM6B expression." (PMID 37275887, 2023). "Notably, KDM6B expression was significantly increased in the lungs of bleomycin-induced pulmonary fibrosis mice, showing a positive correlation with fibronectin and α-SMA, two essential indicators of pulmonary fibrosis." (PMID 37275887, 2023).
acute kidney injury (3 papers, 2023 to 2025). Sudden and sustained deterioration of the kidney function characterized by decreased glomerular filtration rate, increased serum creatinine or oliguria. "Exosomal miR-93-5p from endothelial progenitor cells normally suppresses kidney inflammatory pathways; studies show boosting miR-93-5p in exosomes protected mice from acute kidney injury (AKI) by targeting KDM6B and reducing NF-κB-driven inflammation in renal cells." (PMID 40787977, 2025).
allergic asthma (3 papers, 2021 to 2025). A asthma with a basis in a pathological type I hypersensitivity reaction. "To validate the therapeutic potential of KDM6B inhibition in house dust mite-induced allergic asthma, we conducted in vivo administration of GSK-J4 in a murine disease model." (PMID 40503225, 2025).
Anxiety (3 papers, 2022 to 2025). Intense feelings of nervousness, tension, or panic often arise in response to interpersonal stresses. "This was associated with increased anxiety-like behaviors as well as decreased KDM6B occupancy and increased H3K27me3 occupancy at the Arc synaptic activity response element (SARE) site and promoter." (PMID 38389820, 2023). "This evidence suggests that AIE leads to increased H3K27me3 at the Arc promoter by downregulating the activity of KDM6B, causing decreased Arc expression and increased anxiety-like behaviors in adulthood." (PMID 38389820, 2023). "However, compared to wild-type controls, both male and female mutant mice had fewer marbles buried (male: F1, 28 = 8.52, p = 0.0069, female: F1, 24 = 3.88, p = 0.04), suggesting Kdm6b haploinsufficiency causes lower levels of anxiety-like behaviors in home cages." (PMID 35711692, 2022). "This study also employed the targeted knockdown of Kdm6b and Arc eRNA in the CeA of control rats via small interfering (si)RNA infusion, which induced anxiety‐like behaviours and mimicked the histone modifier and modification changes observed after AIE." (PMID 41190727, 2025). "To further confirm that the heterozygous Kdm6b-KO mice had reduced anxiety-like behaviors, we used the marble-burying task, a test reflecting repetitive behavior related to anxiety, to measure the levels of anxiety-like behaviors of wild-type and mutant mice." (PMID 35711692, 2022). "Additionally, increasing H3K27me3 by knocking down Kdm6b in the CeA of adult ethanol‐naïve rats induced an anxiety‐like phenotype resembling that of adult AIE rats." (PMID 41190727, 2025). "Hence, the collective results suggest that Kdm6b haploinsufficiency reduces anxiety-like behaviors under conditions with low or high stress, which appears to prominently affect male mice." (PMID 35711692, 2022). "Interestingly, knockdown of KDM6B via siRNA infusion induced the same effects in alcohol-naïve adults: increased anxiety-like behaviors, decreased Arc eRNA and mRNA expression, decreased KDM6B occupancy, and increased H3K27me3 occupancy at Arc regulatory sites." (PMID 38389820, 2023).
chronic myelomonocytic leukemia (3 papers, 2018 to 2023). A myelodysplastic/myeloproliferative neoplasm which is characterized by persistent monocytosis, absence of a Philadelphia chromosome and BCR/ABL fusion gene, fewer than 20 percent blasts in the bone marrow and blood, myelodysplasia, and absence of PDGFRA or PDGFRB rearrangement. "In chronic myelomonocytic leukemia, KDM6B overexpression results in activation of innate immune genes, such as S100A9, TLR and C3, indicating that KDM6B is involved in tumor immune microenvironment." (PMID 34950587, 2021).
diffuse intrinsic pontine glioma (3 papers, 2017 to 2021). A neuroglial tumor that arises from the middle portion of the brain stem. "Beside KDM1, KDM4A and KDM5A/5B are up-regulated in TMZ-resistant GB cells, KDM4B is up-regulated in response to irradiation and KDM6B was identified as a possible therapeutic target in the childhood Diffuse Intrinsic Pontine Glioma (DIPG)." (PMID 28432280, 2017). "Lysine demethylase 6B (KDM6B) was overexpressed in GBM tissues and treatment with KDM5B specific inhibitor GSK-J4 significantly improved survival in GBM models of diffuse intrinsic pontine gliomas." (PMID 34361090, 2021). "In particular, KDM5A is involved in the acquisition of temozolomide (TMZ) resistance in adult GB cells and UDX/KDM6B regulates H3K27 methylation, which is involved in the pediatric diffuse intrinsic pontine glioma (DIPG)." (PMID 31238504, 2019).
esophageal cancer (3 papers, 2021 to 2022). A primary or metastatic malignant neoplasm involving the esophagus. "In this regard, it was shown that hypoxia-related induction of the Hif-1α transcription factor stimulated the expression of KDM3A and KDM6B in esophageal cancer cells." (PMID 35326475, 2022). "On the contrary, the KDM6B expression level increased in the tumor tissues of CHOL (cholangiocarcinoma), HNSC (head and neck squamous cell carcinoma) (both p < 0.001), ESCA (esophageal carcinoma) and KIRC (kidney renal clear cell carcinoma) (both p < 0.05)." (PMID 35783266, 2022). "Moreover, the knockdown of KDM6B led to reduced levels of stemness markers, i.e., the reduced expression of CD44, Bmi1, Nanog, and Oct4, and diminished the proportion of side population cells in esophageal cancer cells." (PMID 35326475, 2022).
Hepatic steatosis (3 papers, 2022 to 2024). Steatosis is a term used to denote lipid accumulation within hepatocytes. "Liver-specific downregulation of KDM6B resulted in intrinsic mitochondrial β-oxidation defects, which further led to hepatic steatosis and insulin and glucose intolerance." (PMID 37185761, 2023). "Moreover, KDM6B was also involved in defective autophagy and hepatic steatosis in NAFLD." (PMID 37185761, 2023). "We verified that transcription factor ISL1 cooperated with demethylase KDM6B to upregulate lipid metabolizing enzyme SNAI1, so as to protect against improve NAFLD, including reducing the degree of hepatic steatosis, plasma lipid concentration, and lipid accumulation in cells." (PMID 35100965, 2022). "Although liver-specific downregulation of KDM6B could trigger hepatic steatosis, the evidence for changes in KDM6B expression in experimental NAFLD is still lacking." (PMID 37185761, 2023).
lung adenocarcinoma (3 papers, 2020 to 2025). A carcinoma that arises from the lung and is characterized by the presence of malignant glandular epithelial cells. "We explored the characteristic distribution of these genes in the tumor immune microenvironment and identified two A-ERGs, KDM6B and KANSL1, as potential diagnostic biomarkers for lung adenocarcinoma (LUAD)." (PMID 40832611, 2025). "In addition, the results showed that the KDM6B expression correlates with the degree of the infiltration of tumor-associated fibroblasts in various cancers, including BRCA, HNSC (head and neck squamous cell carcinoma), HPV−, LIHC, LUAD (lung adenocarcinoma), OV, PAAD, SKCM, and SKCM−metastasis." (PMID 35783266, 2022).
lymphoma (3 papers, 2023 to 2025). A malignant (clonal) proliferation of B- lymphocytes or T- lymphocytes which involves the lymph nodes, bone marrow and/or extranodal sites. "The synergistic effect of NOTCH1 and KDM6B mutations therefore may accelerate lymphoma progression by activating oncogenic pathways via chromatin remodeling." (PMID 38566223, 2024). "Additionally, EBV induces the expression of KDM6B; a histone demethylase that removes me3 at H3K27 contributing to lymphoma development." (PMID 41016387, 2025).
metastatic prostate carcinoma (3 papers, 2013 to 2018). A carcinoma that arises from the prostate gland and has spread to other anatomic sites. "KDM6A mutations have been detected in some tumors, whereas KDM6B is upregulated in some cancers, particularly metastatic prostate carcinomas." (PMID 23673719, 2013). "KDM6B upregulation has been reported in metastatic prostate carcinomas." (PMID 23673719, 2013). "Finally, JMJD3 (KDM6B) is progressively overexpressed in metastatic prostate cancer." (PMID 29888169, 2018).
myeloid malignancies (3 papers, 2019 to 2024). "Herein we employed genetic and pharmacologic approaches to evaluate the therapeutic potential of targeting KDM6B in ASXL1 mutation–associated myeloid malignancies." (PMID 37917239, 2024). "This preclinical finding provides compelling evidence that targeting KDM6B may be a therapeutic strategy for myeloid malignancies with ASXL1 mutations." (PMID 37917239, 2024). "This study provides solid preclinical evidence that KDM6B may serve as a therapeutic target for patients with ASXL1 mutation–associated myeloid malignancies." (PMID 37917239, 2024). "Importantly, our study provides scientific evidence for the therapeutic potential of targeting KDM6B in treating ASXL1 mutation–associated myeloid malignancies." (PMID 37917239, 2024). "The data we have presented herein demonstrate that heterozygous deletion of Kdm6b blocks the development of ASXL1 mutation–mediated myeloid malignancies, and that the KDM6B inhibitor GSK-J4 likewise attenuates ASXL1-mutated leukemic cell growth and tumor burden in preclinical mouse models." (PMID 37917239, 2024). "Our results suggest an oncogenic role of Kdm6b-mediated H3K27me3 downregulation in EVI1-induced myeloid malignancies." (PMID 39680456, 2024). "Heterozygous deletion of Kdm6b blocks the development of ASXL1aa1–587–mediated myeloid malignancies." (PMID 37917239, 2024). "Importantly, inhibition of KDM6B restored H3K27me3 levels in Asxl1Y588XTg Kdm6bΔ/+ BM cells, prompting us to initiate preclinical studies to determine whether targeting KDM6B could potentially benefit patients with ASXL1 mutation–associated myeloid malignancies." (PMID 37917239, 2024). "Together, these data suggest that heterozygous deletion of Kdm6b in Asxl1Y588XTg mice is sufficient to reverse the hematologic abnormalities due to ASXL1aa1–587 expression and prevent the progression of ASXL1aa1–587-mediated myeloid malignancies." (PMID 37917239, 2024). "Our findings highlight the presence of the EVI1/KDM6B/H3K27me3/LAPTM4B signaling axis in EVI1-overexpressed myeloid malignancies and suggest the therapeutic potential of inhibition of the KDM6B/H3K27me3/LAPTM4B signaling axis in patients with EVI1hi malignancies." (PMID 39680456, 2024). "Heterozygous deletion of Kdm6b in Asxl1Y588XTg mice restores the HSC pool, normalizes the biased myeloid differentiation, and prevents the development of ASXL1aa1–587-driven myeloid malignancies." (PMID 37917239, 2024). "Furthermore, heterozygous deletion of Kdm6b decreased the HSPC pool, restored their self-renewal capacity, prevented biased myeloid differentiation, and abrogated progression to myeloid malignancies in Asxl1Y588XTg mice." (PMID 37917239, 2024).
myocardial infarction (3 papers, 2022). Gross necrosis of the myocardium, as a result of interruption of the blood supply to the area, as in coronary thrombosis. "Analysis of human blood sample sequencing datasets and mouse myocardial infarction sequencing datasets as well as cardiomyocyte hypoxia experiments indicated that FRGs ALOX5, CAMKK2, KDM6B, LAMP2, PTEN, PTGS2, and ULK1 may be potential biomarkers of AMI." (PMID 36407421, 2022).
steatosis (3 papers, 2020 to 2022). Increased lipid within the cytoplasm of cells. "In this study, we identified that ISL1 had interacted with H3K27me3 demethylase KDM6B to promote the expression of SNAI1, by which lipogenesis and steatosis were attenuated while lipolysis was promoted in the mice models of NAFLD." (PMID 35100965, 2022). "Oil red O staining showed that knocking down KDM6B while overexpressing ISL1 inhibited steatosis, while knocking down ISL1 while overexpressing KDM6B did not inhibit steatosis." (PMID 35100965, 2022).
thyroid cancer (3 papers, 2021 to 2022). "In the COSMIC database, the KDM6B mutational frequency is 4.2% (44 mutated thyroid carcinomas out of 1040 tested, accessed Feb 7th, 2021)." (PMID 33827048, 2021). "A high level of KDM6B was related to poor OS (overall survival) outcomes for THCA (thyroid carcinoma), while a low level was correlated with poor OS and DFS (disease-free survival) prognosis of KIRC." (PMID 35783266, 2022). "Intriguingly, we found that several histone demethylases such as KDM5B, KDM1A, KDM6B, KDM5A and KDM1B, were enriched in thyroid cancer spheres compared to non-CSCs." (PMID 35198054, 2022).
breast invasive carcinoma (2 papers, 2018 to 2022). "KDM6B is a demethylase that specifically demethylates H3K27me3, it is required by TGF beta induced EMT in mammary cells, and is highly expressed in invasive breast cancer." (PMID 30547810, 2018).
colorectal tumor (2 papers, 2025). "In summary, 5-AVA may interact with KDM6B, regulate the Wnt/β-catenin signaling pathway by affecting the methylation of DKK2, and promote the development of colorectal tumors." (PMID 40340623, 2025).
Hypertension (2 papers, 2021 to 2025). The presence of chronic increased pressure in the systemic arterial system. "Decreased KDM6B protein expressions were noted in those with a high hypoxic load, and associated with a higher risk for incident cardiovascular events or hypertension." (PMID 34667186, 2021). "OSA patients with low KDM6B protein expression (< 0.21 ng/μl, n = 23) had higher risk for incident cardiovascular events or hypertension in the following 3 years (p = 0.014 by Log-Rank test) than those with high KDM6B protein expression (≧0.21 ng/μl, n = 33)." (PMID 34667186, 2021).
lymph node metastasis (2 papers, 2019 to 2021). "We show that the expression level of KDM6B increased significantly in patients with lymph node metastasis." (PMID 34001062, 2021). "However, Our findings illustrate that the expression level of KDM6B was significantly increased in patients with lymph node metastasis." (PMID 34001062, 2021). "However, the expression level of KDM6B was obviously increased in patients with lymph node metastasis." (PMID 34001062, 2021).
medulloblastoma (2 papers, 2017 to 2022). A malignant, invasive embryonal neoplasm arising from the cerebellum. "Intermediate expression for EZH2 and H3K27me3 was found for SHH medulloblastoma samples, with both low and high expression of KDM6A and KDM6B." (PMID 29108280, 2017).
multiple sclerosis (2 papers, 2020 to 2021). A progressive autoimmune disorder affecting the central nervous system resulting in demyelination. "The H3‐K27 demethylase Kdm6b (gene: KDM6B), also known as Jmjd3, was one of the targets of erythrocyte‐derived EV miRNAs that were decreased in multiple sclerosis." (PMID 32508012, 2020).